FAM178B (family with sequence similarity 178 member B)
Synonyms: LOC51252
Tractability: PROTAC: ubiquitination databases record sites on it.
Gene: Protein-coding gene on chromosome 2 (96,875,882 to 96,986,580, reverse strand). Ensembl gene ENSG00000168754.
Subcellular location (Human Protein Atlas): Nuclear speckles; Golgi apparatus
Genetic constraint (gnomAD): Loss-of-function variants: 67 observed, 73.63 expected, observed/expected ratio (o/e) 0.91, 90% interval 0.75 to 1.12. The upper end of that interval is the gene's LOEUF score, 1.12, which puts it in group 4 of 6, group 1 being the genes least tolerant of losing a copy. Missense variants: 714 observed, 763.31 expected, observed/expected ratio (o/e) 0.94, 90% interval 0.88 to 1. Synonymous variants: 347 observed, 325.22 expected, observed/expected ratio (o/e) 1.07, 90% interval 0.98 to 1.17.
Homologues: Orthologues: chimpanzee FAM178B (98% identical), macaque FAM178B (92% identical), pig FAM178B (70% identical), dog FAM178B (70% identical), rat Fam178b (63% identical), mouse Fam178b (58% identical). Paralogues in human: SLF2 (27% identical).
Diseases named in the same sentence as FAM178B in open-access papers:
FAM178B is named in the same sentence as 4 diseases in open-access papers, as found by Europe PMC text mining. Sharing a sentence is not in itself a finding about the gene and the disease. The quoted sentences say what the papers report.
glioma (2 papers, 2021 to 2022). A benign or malignant brain and spinal cord tumor that arises from glial cells (astrocytes, oligodendrocytes, ependymal cells). "It is a protein-coding gene with an unrecorded function, and a recent transcriptome-wide study identified FAM178B as a novel susceptibility gene for glioma." (PMID 36527158, 2022). "Our study has revealed causal evidence for three novel genes (RETREG2, FAM178B and MVB12B) associated with glioma risk." (PMID 33504897, 2021). "RETREG2 (or FAM134A), FAM178B and MVB12B appear to be novel findings related to glioma risk." (PMID 33504897, 2021). "The MR and colocalisation results suggested that genetically predicted increased gene expression of 12 genes were associated with glioma, GBM and/or non-GBM risk, three of which are novel glioma susceptibility genes (RETREG2/FAM134A, FAM178B and MVB12B/FAM125B)." (PMID 33504897, 2021).
COVID-19 (1 paper, 2025). A disease caused by infection with severe acute respiratory syndrome coronavirus 2. "By 6 weeks post-inclusion, COVID-19 hypermethylation of genes with the highest fold-change compared to healthy controls included FAM178B, FYN, TMCC1, TMEM212-AS1, and FIG4, while the top five hypomethylated genes were GIT2, PDGFRB, SEMA6D, TNFAIP8, and ETV6." (PMID 41227320, 2025).
cancer (2 papers, 2021). A tumor composed of atypical neoplastic, often pleomorphic cells that invade other tissues. "ANKRD36 has been reported to be coexpressing and interacting with other genes on locus 2q11.2, including ANKRD36C, ITPRIPL1, FAHD2B, FAM178B and CNNM3, which shows that ANKRD36 is involved in some important biological networks associated with cancers." (PMID 34827175, 2021). "ADORA1 and the top 4 significant genes, including MYBPH, FAM178B, CHI3L1 and METTL7B were selected as the hub genes for genetic variation, interrelationship, cancer pathway and drug susceptibility analysis." (PMID 34093805, 2021).
FAM178B also shares sentences with these, for which no sentence is quoted: tumor (1 paper).